RAG2 (recombination activating 2)
Diseases named in the same sentence as RAG2 in open-access papers (continued):
Sharing a sentence is not in itself a finding about the gene and the disease.
Omenn syndrome (17 papers, 2009 to 2024). An inflammatory condition characterized by erythroderma, desquamation, alopecia, chronic diarrhea, failure to thrive, lymphadenopathy, and hepatosplenomegaly, associated with severe combined immunodeficiency (SCID). "Missense mutations in either RAG-1 or RAG-2 genes are also observed in humans with an analogous form of autosomal recessive SCID known as Omenn syndrome." (PMID 29181194, 2017). "Omenn Syndrome can be caused by mutations in Rag1 and Rag2, or rarely by mutations in the NHEJ factor Artemis, in the IL-7 receptor alpha chain or in the RNase mitochondrial RNA processing (RMRP) gene." (PMID 25849362, 2015). "It is possible that Rag1V779M is deficient in V(D)J recombination because it fails to interact with some key regulatory factor in vivo, and is therefore deficient in coupled cleavage, analogous to the Rag2 mutations described in other Omenn Syndrome patients." (PMID 25849362, 2015). "SCID patients had disease-causing mutations in RAG1 or RAG2 (n = 4, two of them presented with Omenn syndrome), IL2RG (n = 4, one of them with confirmed maternal engraftment), NHEJ1 (n = 1), CD3E (n = 1), ADA (n = 1), JAK3 (n = 3, two of them with maternal engraftment) and DCLRE1C (n = 1)." (PMID 32265901, 2020). "However, patients with hypomorphic mutations in RAG1 or RAG2 that display partial V(D)J recombination activity can give rise to a wide spectrum of clinical and immunological phenotypes, ranging from Omenn syndrome (OS) to atypical SCID6." (PMID 30872621, 2019). "Furthermore, spontaneously increased serum IgE levels are detected in MHC-II-deficient and T-lymphopenic mice or in Omenn syndrome patients with reduced Rag1 or Rag2 activity." (PMID 26523376, 2015). "Future studies will test the hypothesis that hypofunctional Rag1 and Rag2 mutants can confer susceptibility to Omenn Syndrome by impairing the post-cleavage stage of V(D)J recombination." (PMID 25849362, 2015). "Indeed, more than 90% of Omenn Syndrome cases are attributable to hypomorphic mutations in Rag1 and Rag2." (PMID 25849362, 2015). "In addition to causing the SCID phenotype, hypomorphic mutations in RAG1 or RAG2 can lead to partially impaired V(D)J recombinational activity resulting in Omenn syndrome (OS)." (PMID 19912631, 2009). "One specific example where we improve the prediction of gene–disease associations is for the disease Omenn syndrome (OMIM:603554) which is associated with three genes: DCLRE1C (ENTREZ:64421), RAG2 (ENTREZ:5897) and RAG1 (ENTREZ:5896)." (PMID 37550716, 2023). "Genetic studies of polymorphisms in wild-type and Omenn syndrome patients as well as biochemical data characterising recombinatorial competence of Omenn syndrome mutants suggest that RAG-1 and RAG-2 mutants exhibit lower efficiency of V(D)J recombination." (PMID 29181194, 2017). "The majority of mutations in Omenn syndrome are missense mutations in recombinase activating genes RAG1 and RAG2." (PMID 25161792, 2014). "Omenn syndrome (OS) shares the genetic aetiology of T-B-NK+ SCID, with mutations in RAG1, RAG2, or DCLRE1C." (PMID 19912631, 2009). "P3 received a conditioned Haplo for homozygous RAG2 Omenn syndrome." (PMID 35579633, 2022).
Autoimmunity (15 papers, 2015 to 2024). The occurrence of an immune reaction against the organism's own cells or tissues. "Hypomorphic RAG1 or RAG2 mutations cause primary immunodeficiencies and can lead to autoimmunity, but the underlying mechanisms are elusive." (PMID 34622798, 2021). "Depending on the types of genetic mutations in the RAG1 or RAG2 genes, autoimmunity associated with expansion of oligoclonal T cells and production of autoantibodies is also often observed in affected patients." (PMID 29734775, 2018). "We made use of a widely used model for peripheral autoimmunity wherein we transferred purified naive CD45RBhi CD4+ T cells from Itgax-Cre control mice into T cell–deficient Rag2−/− mice." (PMID 28130292, 2017). "The most often used animal models are the Rag1 and Rag2 knockout (KO) mice and rats, which are characterized by the absence or abnormality of B and T lymphocyte development, autoimmunity, and inability to mount adequate adaptive immunity to infections." (PMID 29734775, 2018). "To note, F5 TCR-transgenic mice in a RAG2-deficient background (RAG2-KO) do not develop any intestinal inflammation or autoimmunity." (PMID 35426367, 2022). "The adoptive transfer of T cells from mTECΔMHCII mice into Rag2-/- recipients induces autoimmunity." (PMID 35188458, 2022). "Although the Rag2 KI/EGFP mice used as murine OS model helped us to understand the detailed pathogenesis of OS and autoimmunity, whether the R229Q mutation itself is sufficient to cause full development of OS and severely affect immunological disorder is still not clear." (PMID 30872621, 2019). "Together, these results suggest that XCR1 CAR-T cells engraft in immunodeficient RAG2−/− mice and eliminate DC1 in lymphoid organs without acute autoimmunity." (PMID 37965348, 2023).
lymphoma (14 papers, 2006 to 2024). A malignant (clonal) proliferation of B- lymphocytes or T- lymphocytes which involves the lymph nodes, bone marrow and/or extranodal sites. "For this purpose, Rag2– γc– mice (n = 22) were intravenously injected with CD19/CD80/CD86-positive Raji lymphoma cells and treated with CAR (2nd Gen) T cells, corresponding to the Kymriah product (Novartis)." (PMID 38340727, 2024). "A few mice had to be excluded from further analyses due to lymphoma development as is commonly observed in rag2-/- and severe combined immunodeficient (SCID) mice." (PMID 32046143, 2020). "Lower but not significant tumor growth was noted in the wild type mice exposed to UV radiation after the injection of the lymphoma cells (13%, p < 0.0001 vs. Rag2-/- control, Fisher exact test)." (PMID 21269511, 2011). "Lymphoma induction by C91/PL-derived cells in Rag2-/-γc-/- mice." (PMID 29951044, 2018). "These cells were then i.p inoculated into 4–5-day-old Rag2-/-γc-/- mice at different doses and all (7 of 7) animals belonging to the group injected with the higher dose developed a very aggressive and invasive lymphoma with a short latency period (median survival, 15 days)." (PMID 29951044, 2018). "Progressive tumor growth was only noted when the lymphoma cells were injected into the Rag2-/- recipients (100% tumor incidence), significantly lower tumor incidence occurred when the cells were transplanted into wild-type mice (7%, p < 0.0001 vs. Rag2-/- control, Fisher exact test)." (PMID 21269511, 2011). "We observed a frequency of 82% in Rag2-/-γC-/- mice, suggesting that the most severe immune deficient mouse models are more vulnerable to development of EBV-driven lymphoma, presumably due to the absence of cytotoxic T cells which play a critical role in the control of latent EBV infected B-cells." (PMID 29145505, 2017). "While there was no lymphoma observed in GCB-LMP1/2 mice at the immune-competent state, the transfer of purified B cells after the elimination of interacting T cells from GCB-LMP1/2 mouse spleen of these mice into the immunocompromised Rag2-deficient mice resulted in LMP1/2A+ B lymphoma development." (PMID 36077655, 2022).
sarcoma (14 papers, 2011 to 2026). A usually aggressive malignant neoplasm of the soft tissue or bone. "A previous study showed that immunodeficient (RAG2−/−x γc−/−) mice were more susceptible to MCA (3-methylcholanthrene)-induced sarcoma than were syngeneic RAG2−/− and wide-type (WT) mice." (PMID 36613591, 2022). "When transplanted into RAG2-deficient mice, all sarcomas grew progressively with equivalent kinetics." (PMID 24860567, 2014). "In contrast, when the tumor cells were injected into immunocompetent wild-type hosts, all sarcomas from wild-type mice grew progressively, while 8 of 20 (40%) sarcomas from RAG2-deficient mice were rejected." (PMID 24860567, 2014). "By using the chemical carcinogen methylcholanthrene, sarcomas were induced either in wild-type mice or in RAG2-deficient mice, which lack both T and B cells." (PMID 24860567, 2014). "Similarly, it was observed that several highly immunogenic and poorly tumorigenic sarcomas from RAG-2 deficient mice were converted into poorly immunogenic, and thus highly tumorigenic, when rendered insensitive to IFNγ." (PMID 35251003, 2022). "Experiments with mice lacking the recombinase activating gene (RAG)-2, and thus lacking lymphocytes T, B and natural killer (NK) T cells, further demonstrated that tumor development in mice was controlled by the immune system, as RAG-2 deficient mice were more sensitive to MCA-induced sarcomas." (PMID 35251003, 2022). "O’Sullivan describes the role of NK cells in educating macrophages toward an anti-tumoral state that act as crucial effectors in immunoediting in a RAG2−/− x γc (−/−) mouse model of induced sarcoma." (PMID 33608544, 2021). "Strikingly, this abrogated ALCL development in favour of hepatocellular carcinomas and sarcoma, as seen in the NA/RAG2−/−/OT1 mice." (PMID 26753883, 2016). "To explore the mechanism of IgG production in sarcoma cells, we investigated the expression of several enzymes, including RAG1, RAG2 and AID." (PMID 21731691, 2011). "MCA-induced sarcoma cell lines derived from RAG2−/− (30% regression) and RAG2−/−x γc−/− (70% regression) mice failed to form tumors when transplanted into syngeneic WT mice." (PMID 36613591, 2022).
primary immunodeficiency (11 papers, 2015 to 2025). "RAG2-SCID is a primary immunodeficiency caused by mutations in Recombination-activating gene 2 (RAG2)." (PMID 37891182, 2023). "RAG2-SCID is a primary immunodeficiency caused by mutations in Recombination-activating gene 2 (RAG2), a gene intimately involved in the process of lymphocyte maturation and function." (PMID 37891182, 2023). "Using a novel strategy of targeted resequencing a multitude of known primary immunodeficiencies genes in patients with predominantly antibody deficiency we identified compound heterozygous mutations in RAG1 or RAG2 in the two patients described." (PMID 26186701, 2015). "RAG1 and RAG2 mutations are reportedly frequent in multiple primary immunodeficiencies." (PMID 38240953, 2024). "To validate this data, we investigated papers reporting the role of RAG1 and RAG2 in primary immunodeficiencies and their methylation status." (PMID 38240953, 2024). "Among 15 perturbed pathways, the pathways for primary immunodeficiency, B cell receptor signaling, T cell receptor signaling, Th17 cell differentiation, and Th1 and Th2 cell differentiation were significantly dysregulated in the infected Rag2−/− mice as compared to the B6 mice." (PMID 38675952, 2024). "For example, several immunodeficient rabbit lines have been produced by knocking out of genes such as Il2rg, Foxn1, and Rag2; these animals are expected to make valuable contributions to regenerative medicine, cancer and primary immunodeficiency, as comprehensively reviewed elsewhere." (PMID 33584832, 2021). "The SGM rabbits we produced in this study can be used for modeling corresponding human primary immunodeficiency diseases: FOXN1 (OMIM# 600838), IL2RG (OMIM# 300400), RAG2 (OMIM# 601457), and PRKDC (OMIM# 600899)." (PMID 28939872, 2017).
lymphopenia (10 papers, 2012 to 2025). Reduction in the number of lymphocytes. "Patient B displayed a significant B-cell lymphopenia, and a comparable impairment in B cell differentiation was observed in core RAG2-deficient mice, as in this animal model mature circulating B cell numbers were severely reduced." (PMID 26186701, 2015). "This study aims to provide detailed phenotypes of F344-Il2rg KO, Rag2 KO, and Il2rg/Rag2 KO rats, shedding light on their overall health status, physiological parameters, and histopathological features in lymphoid organs correlated with the severe lymphopenia caused by Il2rg and Rag2 KO." (PMID 39731164, 2024). "Since lymphocyte-deficient RAG2-/- mice provoke the lymphopenia-driven proliferation of T cells in vivo, these data indicate that 4-1BB triggering may generate the environment that is similar to the condition for lymphopenia-driven proliferation of T cells." (PMID 25962156, 2015). "SERCA proteins modulate intracellular Ca2+ levels to regulate RAG1 and RAG2 gene expression and V(D)J recombination and defects in SERCA functions cause lymphopenia." (PMID 39943104, 2025). "During experiments, Il2rg KO, Rag2 KO and Il2rg/Rag2 KO rats showed decreased white blood cells and systemic lymphopenia, with reduced CD4+, CD8+ T cells and CD161+ NK cells." (PMID 39731164, 2024). "To evaluate homeostasis of the mature B cell pool during lymphopenia, we turned to an adoptive transfer model of purified follicular B cells into Rag2–/– mouse recipients." (PMID 35579963, 2022). "To evaluate how mature B cell populations respond to lymphopenia, we adoptively transferred FoB cells into Rag2–/– lymphopenic mice, which lack mature B and T cells." (PMID 35579963, 2022). "Interestingly, donor-derived MZB cells in B6 recipients had more differentially expressed genes compared with both B6 MZB cells and donor-derived MZB cells in Rag2–/– recipients, suggesting that lymphopenia enhanced the acquisition of the MZB cell transcriptional program in B cells." (PMID 35579963, 2022). "At day 8, donor-derived cells sorted as MZB cells in Rag2–/– recipients clustered tightly with B6 MZB cells with very few differentially expressed genes, indicating that lymphopenia-induced transdifferentiation fully reprogrammed FoB cells to a MZB cell state." (PMID 35579963, 2022). "Thus, in the context of RAG2 lacking the C terminus domain (Rag2c/c mutant, also referred to as core RAG2), XLF deficiency leads to a profound lymphopenia associated with a severe defect in V(D)J recombination." (PMID 27601299, 2016).
melanoma (10 papers, 2013 to 2023). A malignant, usually aggressive tumor composed of atypical, neoplastic melanocytes. "To test this hypothesis, we compared the effects of LTX-315 treatment in either wild-type or Rag2–/– (lymphocyte deficient) mice bearing B16F10 melanoma tumors." (PMID 31799501, 2019). "TTDEs were isolated from different mouse tumor models: human melanoma WM9 cells established in Rag2−/− mice, and murine melanoma B16-F10 established in C57BL/6 mice and Rag2−/− mice." (PMID 35835783, 2022). "We now further demonstrate the utility of the 8HUM mouse using a murine melanoma cell line as a syngeneic tumour and also present an immunodeficient version 8HUM_Rag2-/- - for use in xenograft studies." (PMID 37065929, 2022). "To determine if the phenotypic difference exhibited in Rag2-/- and Rag2-/- PD-1-/- mice is clinically translatable, we injected a cohort of Rag2-/- mice with B16 melanoma cells." (PMID 34531874, 2021). "We also reported a significant increase of the expression of RAG1 and RAG2, genes known to be involved in B cell and T cell receptor rearrangements, in melanoma compared to normal skin, consistent with our findings of secondary lambda rearrangement and VH replacement." (PMID 37291228, 2023). "To assess the transplantation potential of our melanoma model, we isolated nf1/pten-mutant melanoma cells and transplanted them intraperitoneally into the optically clear immunodeficient rag2E450fs(casper) zebrafish (designated “rag2−/−”)." (PMID 34331013, 2021). "However, each of the remaining subsets was transferred intravenously into γc RAG2−/− mice followed by challenge with B16 melanoma." (PMID 23776508, 2013). "aceNKPs (CD45.2) were adoptively transferred intravenously into sublethally irradiated Rag2–/–Il2rg–/– (CD45.1) recipients and after ~6 wk these mice were challenged with the B16F10 melanoma cell line." (PMID 36442116, 2022). "To demonstrate the crosslinking of IgM with B16F10 melanoma, we seeded B16F10 cells on Lab-Teks and added fresh serum from naïve WT, IgHEL,cAicda, Rag2−/−, and muMT mice for 30 min." (PMID 34608861, 2021). "In melanoma, NOD/SCID and RAG2−/− mice were injected melanoma cells isolated from melanoma patients, and the results showed PAS-positive and CD31-negative channel formation in humanized xenografts." (PMID 32169087, 2020).
colon carcinoma (9 papers, 2007 to 2025). "In contrast, MDR1A deficiency in RAG2 KO mice that lack both B and T cells aggravated colonic tumor progression." (PMID 28686677, 2017). "However, injection of human colon cancer LS180 cells into the tail vein of P‐selectin‐deficient Rag2‐null mice also resulted in a marked reduction in micrometastasis to the lung compared to wildtype Rag2‐null mice." (PMID 40327521, 2025). "marked tumor progression of MDR1A/RAG2 dKO which lack B (and T) cells, we asked next what functional role B cells may play in colon tumor development in MDR1A deficiency." (PMID 28686677, 2017). "In addition, they found that the human colon cancer cells (SW480) expressed SNC73, Ig heavy chain α1, recombination activating gene 1 (RAG1), and RAG2." (PMID 34226529, 2021). "Mice lacking Rag2 developed mainly intestinal adenomas and colon carcinomas, which usually occur following intestinal infection." (PMID 29881389, 2018).
parasitemia (9 papers, 2011 to 2025). "We observed that similar to T-bet deficiency, Rag2-/-γc-/- mice had very few inflammatory DCs, further demonstrating that ILC1s are essential for the presence of inflammatory DCs during parasite infection." (PMID 33465134, 2021). "Infected RAG2−/− mice had significantly lower parasitemia, better survival rate, and lesser body weight loss compared with those of infected WT mice." (PMID 28874800, 2017). "Upon infection with T. brucei, in both Rag2-/- and Jht-/- mice, parasitemia increased until day 6 post-infection, but instead of undergoing a quick reduction, parasite numbers persisted at very high levels." (PMID 34525131, 2021). "N67C-infected RAG2−/− mice had significantly lower parasitemia, higher body weight, and longer survival time than the infected WT mice." (PMID 28874800, 2017). "In contrast, total parasite biomass (determined by imaging the whole body) remained low in the RAG2−/− mice until it increased steadily from day 9 onwards, paralleling the increase in parasitemia." (PMID 21494565, 2011). "Parasitemia curve of T. congolense 1/148 in WT or RAG2 KO mice, measured by hemocytometry." (PMID 35787830, 2022). "The six 8HUM/Rag2–/–,which showed some degree of engraftment, were infected with P. falciparum but no detectable parasitemia was observedover the following 7 days, in contrast to the subset of NSG mice, which wereinfected as a positive control group." (PMID 41320957, 2025). "In addition, our preliminary data suggested that metformin treatment did not reduce parasitemia in Rag-2 gene-knockout mice, which lack an adaptive immune system (data not shown)." (PMID 30619302, 2018).